SHH (sonic hedgehog signaling molecule)
Diseases named in the same sentence as SHH in open-access papers (continued):
Sharing a sentence is not in itself a finding about the gene and the disease.
breast carcinoma (58 papers, 2009 to 2025). "The Sonic hedgehog (SHH) pathway, which governs placode development through epithelial–mesenchymal interactions, is also implicated in breast cancer progression." (PMID 40075637, 2025). "Breast cancer etiology is linked to sonic hedgehog (SHH) signaling with a role in mouse glandular development." (PMID 39598664, 2024). "In summary, we found that loss of MED12 promotes GLI3-dependent SHH signaling in breast cancer cells which subsequently leads to enhanced cell proliferation and colony formation ability." (PMID 38915457, 2024). "GLI1 was upregulated which coincided with loss of mono-methylation at histone 3 lysine 4, while SHH was hypomethylated and overexpressed in breast cancer." (PMID 38474826, 2024). "Expression of SHH protein in the Croatian cohort of breast cancer patients was associated with a molecular subtype or more precisely, higher SHH expression was observed in receptor-positive BCs." (PMID 36294994, 2022). "Since SHH pathway dysregulation is reported as an early event in several breast cancer studies, we selected SHH pathway to evaluate the association of FGFR1 and SHH pathway in modulating breast carcinogenesis." (PMID 34722544, 2021). "This is supported by findings that SHH, PTCH1, and GLI1 mutations are exceedingly rare in breast cancer which argues against the potential involvement of mutational activation of the SHH pathway in breast cancer." (PMID 32957513, 2020). "Dysregulation of the SHH pathway is implicated in the development and proliferation of breast cancer." (PMID 32957513, 2020). "Mutations in PTCH1, SMO and SHH genes have been examined in breast cancer: some studies found mutations, while others did not." (PMID 25503972, 2014). "In human breast cancer, high serum SHH levels were associated with poor overall survival." (PMID 37932728, 2023). "Thus, we hypothesize that alterations in MED12 causes dysregulation of SHH signaling in breast cancer cells to subsequently promote oncogenesis." (PMID 38915457, 2024). "The dysregulation of pathways, such as Wnt, FGF, SHH, Notch, EGFR, and BMP, can predispose individuals to breast cancer by promoting abnormal cell proliferation, survival, and tissue remodeling." (PMID 40075637, 2025). "The dysregulation of SHH signaling has been explored as a potential therapeutic target in breast cancer." (PMID 40075637, 2025). "Since prior results have shown a link between loss of MED12 and hyperactivation of GLI3-mediated SHH signaling in prostate cancer and X-linked intellectual disability syndromes, we performed quantitative PCR to determine whether dysregulated signaling also occurs in breast cancer cells." (PMID 38915457, 2024). "The SHH signalling pathway was found to promote glycolysis and breast cancer progression by enhancing the expression of PFKFB3, a key enzyme in the glucose metabolism pathway of breast cancer cells." (PMID 38288377, 2024). "Disruptions of two of the SHH pathway-related factors, patched homolog-1 (PTCH-1) or glioma-associated oncogene-2 (GLI-2), are observed in breast cancer." (PMID 39598664, 2024). "Overall, our results show that solasonine and AB23A are promising targeted therapies for breast cancer cells with dysregulated GLI3-dependent SHH signaling such as is seen in MED12-altered cells." (PMID 38915457, 2024). "Previous reports provided evidence that SHH signaling was involved in drug resistance and directly influenced metastasis in breast cancer." (PMID 36737428, 2023). "This study aimed to evaluate the expression of sonic hedgehog (SHH) and glioma-associated oncogene 1 (GLI-1) in the serum and mammary tumour tissues of dogs." (PMID 37932728, 2023). "We found that normal breast tissue and breast cancer tissue expressed significantly different levels of SHH, PTCH1, SMO, GLI1, and GLI2 (p < 0.05)." (PMID 36142286, 2022).
breast carcinoma (continued). "Taken together, these results reveal that CXCR4, transcriptionally regulated by ETV4, is a mediator in ETV4-induced SHH pathway activation and stem-like traits in breast cancer cells." (PMID 34052833, 2021). "GLI1 overexpression in breast cancer serves as a significant marker of aberrant activation of the SHH pathway driving the formation and progression of breast cancer." (PMID 33494284, 2021). "According to GSEA results, SHH pathway genes were significantly upregulated in FGFR1 patients in both discovery cohorts of breast cancer." (PMID 34722544, 2021). "Nevertheless, expression of SHH pathway components correlates with more aggressive breast cancer subtypes and predicts poor overall survival." (PMID 32957513, 2020). "There is a relationship between CD24 and Sonic hedgehog (SHH), as knocking down CD24 in breast cancer cells have demonstrated increased proliferation, invasion, and tumorigenicity through higher expression of SHH, GLI1, and MMP2." (PMID 32426267, 2020). "SHH has an important role in the erroneous origin of malignancy in breast cancer because it maintains abnormal proliferation and promotes invasion to other tissues (metastasis)." (PMID 32245065, 2020). "Suppression of Hedgehog pathway either by CRISPR mediated SHH knock out or GANT61 altered regulation of EMT markers in breast cancer cells." (PMID 31036836, 2019). "This is the first study to assess the impact of SHH suppression in breast cancer cells using CRISPR mediated knockout models." (PMID 31036836, 2019). "Some studies reported that autocrine activation of SHH is present in colorectal cancer and breast cancer." (PMID 31744214, 2019). "On the contrary, E-cadherin was negatively related to the Hedgehog mediators in the cohort showing the potential involvement of SHH/GLI1 in breast cancer progression." (PMID 31036836, 2019). "Previous studies have shown that SHH is highly expressed in breast cancer, and the SHH-GLI feedback mechanism contributes to the occurrence and the development of breast cancer." (PMID 31898580, 2019). "In conclusion, data suggest that GLI1 reciprocates SHH in breast cancer cells and GANT61 is effectual in curtailing cell viability in dose and time dependent manner." (PMID 31036836, 2019). "Current findings provide firm evidence of involvement of SHH/GLI1 axis in augmenting EMT signals in breast cancer cells." (PMID 31036836, 2019). "To determine the clinical relevance of TSPAN8- and ATXN3-regulated PTCH1/SHH stability, we performed IHC staining of 90 breast cancer specimens and found that the expression of TSPAN8 in the tumor tissue was higher than that in the adjacent non-tumor tissue." (PMID 31253779, 2019). "In order to understand association between altered expression of SHH/GLI1 axis and EMT markers in breast cancer cohort, immunostaining and qRT-PCR was performed." (PMID 31036836, 2019). "In the present study, correlation of SHH/GLI1 axis with EMT markers was assessed in breast cancer cohort." (PMID 31036836, 2019). "It is thereby inferred that SHH/GLI1 axis enhances invasiveness by potentiating the expression of EMT markers in breast cancer cells." (PMID 31036836, 2019). "Gli1 overexpression is revealed to have a close connection with breast cancer as a significant maker of aberrant activation of SHH pathway." (PMID 29113369, 2017). "We found that breast cancers with low expression of the crosstalk molecules, Sonic Hedgehog (SHH) or Slit homolog 2 (SLIT2), have significantly shorter relapse-free survivals than those with high expression." (PMID 28440283, 2017). "The molecular mechanism, in part, involved the PRL-induced upregulation of SHH at the protein level from breast cancer cells." (PMID 27782069, 2016). "We discovered that PRL can escalate the osteolytic aspect of the vicious cycle, by stimulating pre-osteoclasts indirectly to differentiate into osteolytic cells through breast cancer secreted factors, such as SHH." (PMID 27782069, 2016).
breast carcinoma (continued). "The co-culture of breast cancer cells with washed human platelets activated by Cat K up-regulates SHH and the expression of factors, such as PTHrP and TGFβ, that amplify the paracrine Hedgehog signaling." (PMID 26931461, 2016). "SHH overexpression was documented to contribute to breast cancer development and progression in both ERα-positive and negative tumors." (PMID 27548161, 2016). "SHH autocrine signalling within the epithelial cells also appears to be important for cell renewal of cancer stem cells in breast cancer, multiple myeloma and chronic myelogenous leukaemia stem cells." (PMID 22349813, 2012). "Our results show that loss of MED12 leads to enhanced cellular proliferation and colony formation of breast cancer cells through a mechanism that involves activation of GLI3-dependent SHH signaling, a pathway that is central to breast development and homeostasis." (PMID 38915457, 2024). "Furthermore, we successfully found two natural compounds that can potentially combat MED12-altered breast cancer by targeting the GLI3-dependent SHH signaling pathway." (PMID 38915457, 2024). "Importantly, glycolytic production of lactate enhanced TMEM105 expression in breast cancer cells by activating the SHH-MAZ signaling pathway." (PMID 36737428, 2023). "SHH activation may contribute to relapse and can be used as a predictor of postoperative relapse in breast cancer." (PMID 35563449, 2022). "In addition to PTCH1, high SHH, SMO, GLI1, and GLI2 expression levels were all associated with a poor prognosis in breast cancer patients." (PMID 36142286, 2022). "mRNAs of SHH, PTCH1, and GLI1 are highly expressed in breast tumors, inspiring the hypothesis that the SHH pathway may help predict postoperative relapse in breast cancer patients." (PMID 36017236, 2022). "Interestingly, 5 out of 16 SHH pathway genes showed core enrichment in FGFR1-expressed breast cancer patients using leading-edge subset method." (PMID 34722544, 2021). "Similarly, in the second dataset of 327 breast cancer patients, GLI1 overexpression was the only gene in the SHH pathway that showed significant associations with late stage (p = 0.047)." (PMID 34722544, 2021). "Furthermore, breast cancer cell line (MDA-MB-231) was used to investigate the probable association of FGFR1 with SHH and GLI1 in breast cancer progression." (PMID 34722544, 2021). "In addition, AZD4547, SiGLI1, SiSHH, and CRISPR/Cas9-mediated SHH knockout in MDA-MB-231 breast cancer cells was also assessed." (PMID 34722544, 2021). "Based on these findings, it is rational to hypothesize that ETV4 facilitate SHH signaling activation by modulating CXCR4 expression in breast cancer." (PMID 34052833, 2021). "Our study reveals that ETV4 can activate SHH signaling to enhance breast cancer cell stemness." (PMID 34052833, 2021). "In addition, there are data supporting the contribution of SHH signaling to increased proliferation, invasion, and migration of breast cancer cells." (PMID 34203581, 2021). "Moreover, we found elevated expression of CXCR4 in SHH signaling activated breast cancer spheres, indicating that CXCR4 expression is correlated with the activity of SHH pathway." (PMID 34052833, 2021). "In ER+ subtype breast cancer, estrogen triggers the overexpression of SHH and GLI1." (PMID 32962123, 2020). "SHH contributes to tumorigenesis and progression with some types of breast cancer." (PMID 31979397, 2020). "The remainder of this review is dedicated to summarizing the pertinent functions of tGLI1-mediated SHH signaling in glioblastoma and breast cancer, two cancers in which tGLI1 activity has been validated, and how tGLI1 activity can be leveraged to devise novel treatments." (PMID 32957513, 2020). "Therefore, it was confirmed that abrogation of SHH/GLI1 axis have significant impact on regulation of EMT markers in breast cancer cells." (PMID 31036836, 2019).
breast carcinoma (continued). "In addition, a positive association between the expression levels of TSPAN8 and SHH, as well as between PTCH1 and ATXN3, in breast cancer specimens was observed." (PMID 31253779, 2019). "Moreover, recombinant SHH mediated rescue of Hedgehog ablation reinstated the invasive capability of breast cancer cells." (PMID 31036836, 2019). "Analyzing databases for paracrine signaling through receptor-ligand pairs, occurring both on luminal and myoepithelial cells, we found that breast cancers with low expression of the crosstalk molecules SHH and SLIT2 resulted in significantly shorter relapse-free survivals." (PMID 28440283, 2017). "Specifically, the role of canonical, SMO-/SHH-dependent HH signaling and non-canonical, SMO-/SHH-independent HH signaling was addressed, as this pathway has been linked to tumorigenesis including breast cancer." (PMID 26927093, 2016). "Given that the expression of SHH in various breast cancer cell clines and the nuclear translocation of Gli-1 are suppressed by NCTD, it may imply that NCTD can be used to target renewal signaling against CSCs." (PMID 24073010, 2013). "Hence, targeting SHH/GLI1 axis may provide a plausible therapeutic implication for metastatic breast cancer patients." (PMID 31036836, 2019). "Overall, these results suggest that solasonine and AB23A inhibit GLI3-mediated SHH signaling and are therefore promising therapeutic agents for MED12 downregulated breast cancer." (PMID 38915457, 2024). "Analysis of TCGA data showed that SHH and MAZ were significantly overexpressed in breast cancer tissues." (PMID 36737428, 2023). "We also observed that the accumulation of lactate significantly increased SHH, SMO, and GLI1 expression of the SHH signaling pathway in breast cancer cells." (PMID 36737428, 2023). "The aim of this study was to evaluate the expression of SHH and GLI-1 in the serum and mammary tumour tissues of dogs." (PMID 37932728, 2023). "First, we analyzed the expression of SHH, PTCH1, SMO, GLI1, and GLI2 in normal breast and breast cancer tissues through the Oncomine database." (PMID 36142286, 2022). "In the context of breast cancer brain metastasis, we also found BRD4 silencing caused downregulation of two downstream target molecules, Shh and Gli, while BRD4 overexpression improved their expression, suggesting that BRD4 may promote MMP9 expression through SHH signaling pathway in 231-BR cells." (PMID 34421353, 2021). "Here, using large-scale transcriptomic data of 1,425 breast cancer patients, we demonstrated that FGFR/SHH pathway crosstalk leads to poor prognosis of breast cancer patients." (PMID 34722544, 2021). "SHH pathway activation promotes mammary epithelial cell mesenchymal transition (EMT), and regulates mammary cancer stem cell (CSC) self-renewal, and facilitates angiogenesis." (PMID 33494284, 2021). "The researchers found that in breast cancer, downstream SMO targeting is better than upstream SMO when attempting to interrupt SHH signaling." (PMID 31979397, 2020). "The present study was conducted to explore the influence of SHH/GLI1 axis on epithelial mesenchymal transition and invasion in breast cancer cells." (PMID 31036836, 2019). "This led us to investigate the influence of SHH knockout and GANT61 on metastatic potential of breast cancer cells." (PMID 31036836, 2019). "Our analyses of human breast cancer specimens revealed positive correlation among the expression levels of TSPAN8, PTCH1, SHH, and ATXN3." (PMID 31253779, 2019). "Impact of SHH/GLI axis inhibition on modulation of EMT and metastasis in breast cancer cells still needs further explication." (PMID 31036836, 2019). "These experiments strongly suggest that TSPAN8 together with ATXN3 promote the Hedgehog signaling and breast cancer progression by enhancing PTCH1 and SHH expression." (PMID 31253779, 2019). "The present study explored relationship between SHH/GLI1 axis and EMT (Ecadherin, Vimentin and Snail) markers in Pakistani breast cancer cohort." (PMID 31036836, 2019).
breast carcinoma (continued). "Accordingly, expression levels of TSPAN8, PTCH1, SHH, and ATXN3 are positively correlated in human breast cancer specimens, and high TSPAN8 and ATXN3 expression levels correlate with poor prognosis." (PMID 31253779, 2019). "In this study, we observed that activated LKB1 decreased the expression of factors related to Hh reporter activity in MDA-MB-231 breast cancer cells, including of SMO, SHH and GLI1." (PMID 23861764, 2013). "The highly significant correlation between SHH and GLI1 expression characterises GLI1 as a potential functional downstream target of the hedgehog signalling pathway in human breast cancer as well." (PMID 19706168, 2009). "Though prior reports have established links between SHH signaling and breast cancer development, no studies to date have reported the potential role of MED12 in this process." (PMID 38915457, 2024). "SHH expression is induced by NF-κB activation, which in turn promotes CXCL12 secretion in breast cancer cells and regulates the positive feedback loop in breast cancer TME." (PMID 38004606, 2023). "Since SHH and GLI-1 are known to be prognostic markers in human breast cancer and GLI-1 is a critical transcriptional factor, we evaluated the expression of SHH and GLI-1 in normal dogs and dogs with MGT to investigate the relationship between the Hh signalling pathway and canine MGTs." (PMID 37932728, 2023). "Overexpression of SHH, PTCH1, and GLI1 is found in most cases of breast cancer." (PMID 35563449, 2022). "Therefore, we used the Kaplan–Meier plotter website to analyze the effects of SHH, PTCH1, SMO, GLI1, and GLI2 on the prognosis of breast cancer patients." (PMID 36142286, 2022). "Thus, the Hedgehog signaling pathway and its core members, such as SHH and GLI2, play an essential role in the growth regulation of breast cancer." (PMID 36142286, 2022). "To evaluate whether ETV4 stimulate SHH signaling activation, we knocked down ETV4 expression and found decreased protein levels of SHH and GLI1 in ETV4-silenced breast cancer cells." (PMID 34052833, 2021). "Moreover, besides its involvement in breast cancer cell stemness by modulating glycolytic gene expression, we show that ETV4 also activates SHH signaling to promote breast cancer stemness via transcriptionally regulating its target gene CXCR4." (PMID 34052833, 2021). "Aberrant upregulation of SHH affects changes in the tumor microenvironment of breast cancer, whereas type II non-canonical SHH signaling plays a role in the tumor stroma of breast cancer." (PMID 31979397, 2020). "The microenvironment of breast cancer is affected by the type II noncanonical SHH signaling pathway, which can enhance cancer development and metastasis." (PMID 32962123, 2020). "Additionally, both SHH knockout and GANT61 inhibited translocation of GLI1 into nucleus providing the evidence for inactivation of GLI1 in breast cancer cells." (PMID 31036836, 2019). "Moreover, through co-culture experiments, we show that platelets activated by cathepsin K mediated the up-regulation of SHH, PTHrP, OPN, and TGFβ in epithelial-mesenchymal-like cells from patients with Luminal B breast cancer." (PMID 26931461, 2016). "PRL also induces Sonic Hedgehog (SHH) at the protein level in breast cancer cells, although the signal transduction pathway is not known." (PMID 27782069, 2016). "Our study reveals that human platelets activated by Cat K-tumor cells with epithelial-mesenchymal-like transition phenotype predominantly up-regulate SHH, PTHrP, TGFβ, Src, OPN, CD44, and P-selectin, and impact the malignancy of breast cancer cells possibly contributing to their tropism to bones." (PMID 26931461, 2016). "A significant correlation between increased expression of both SHH and GLI1 in human breast cancer would support the hypothesis that aberrant Hh signalling contributes to breast cancer development or progression." (PMID 19706168, 2009).